RASSF1 (Ras association domain family member 1)
Diseases named in the same sentence as RASSF1 in open-access papers (continued):
Sharing a sentence is not in itself a finding about the gene and the disease.
endometrial cancer (8 papers, 2009 to 2025). Primary or metastatic malignant neoplasm involving the endometrium (mucous membrane that lines the endometrial cavity). "The Journal retracts the article titled “Nitric Oxide Donor DETA/NO Inhibits the Growth of Endometrial Cancer Cells by Upregulating the Expression of RASSF1 and CDKN1A”, cited above." (PMID 41217138, 2025).
invasive breast carcinoma (8 papers, 2004 to 2019). A carcinoma that infiltrates the breast parenchyma. "RASSF1 hypermethylation has been detected in carcinoma in situ and invasive breast cancer and is inversely correlated with RNA and protein expression levels and overall survival." (PMID 26510686, 2015). "Hypermethylation of RASSF1 was most frequent, present in 14/17 cases, followed by APC in 12/17, and GSTP1 in 9/17 cases with establishment of an epigenetic monocloncal progression continuum to invasive breast cancer." (PMID 21776373, 2011).
seminoma (7 papers, 2011 to 2025). A radiosensitive malignant germ cell tumor found in the testis (especially undescended), and extragonadal sites (anterior mediastinum and pineal gland). "Epigenetically, seminomas maintain global hypomethylation, while non-seminomas show the promoter hypermethylation of tumor suppressors such as Ras association domain family member 1 isoform A (RASSF1A)." (PMID 40565559, 2025).
Wilms tumor (7 papers, 2004 to 2023). An embryonal neoplasm characterized by the presence of epithelial, mesenchymal, and blastema components. "Both genome-wide analyses identified genes previously known to be hypermethylated in Wilms' tumour, such as RASSF1." (PMID 19956686, 2009).
esophageal cancer (6 papers, 2015 to 2024). A primary or metastatic malignant neoplasm involving the esophagus. "Our results showed that the core components of the Hippo pathway (Mst1/2, LATS1, and Mob1) and the RASSF1 protein coimmunoprecipitated and that their binding was significantly enhanced by rhBMP-2 treatment in both esophageal cancer cell lines." (PMID 27230238, 2016). "In the esophageal cancer lesions, PIK3R1 was expressed in 65.5% (19/29) cases (+: 18; ++: 1; +++: 0), PTEN was expressed in 48.3% (15/31) cases (+: 14; ++: 1; +++: 0), and RASSF1 was expressed in 56.7% (17/30) cases (+: 14; ++: 3; +++: 0)." (PMID 27893424, 2017).
oral squamous cell carcinoma (6 papers, 2010 to 2024). "In oral squamous cell carcinoma, radioresistance was associated with RASSF1 promoter methylation and loss of RASSF1 expression was found to be significantly associated with poor disease-free survival." (PMID 35625825, 2022).
osteosarcoma (6 papers, 2011 to 2025). A usually aggressive malignant bone-forming mesenchymal neoplasm, predominantly affecting adolescents and young adults. "Recently, RASSF1 was also shown to be a tumor suppressor in osteosarcoma." (PMID 21253504, 2011).
head and neck cancer (5 papers, 2013 to 2025). A primary or metastatic malignant neoplasm affecting the head and neck. "In head and neck cancer, hypermethylation of RASSF1 promoter is a frequent event and meta-analysis shows that it is significantly associated with these cancers." (PMID 31712935, 2020). "This hypomethylated set of genes included many genes that have previously been shown to be methylated in head and neck cancer, including RASSF1, CHFR, RUNX3, APC, and CDKN2A (p16)." (PMID 23358896, 2013). "Hypermethylation of promoter regions in head and neck cancer has been shown in many studies, and below we summarize recent studies about p16, PTEN, DAPK, MGMT, ECAD and RASSF1 genes which are frequently analyzed in HNSCC." (PMID 31712935, 2020).
lymphoma (5 papers, 2012 to 2023). A malignant (clonal) proliferation of B- lymphocytes or T- lymphocytes which involves the lymph nodes, bone marrow and/or extranodal sites. "In the second forward screen performed in mice on a Rassf1-null background, 111 Rassf1−/−; SB and 25 Rassf1+/+; SB tumors were predominantly poorly differentiated lymphoma." (PMID 31338332, 2019).
ovarian tumors (5 papers, 2006 to 2017). "CGIs associated with three putative tumor suppressor genes APC, HIC1 and RASSF1 have previously been shown to be frequently hyper-methylated in breast and ovarian tumors when compared to healthy tissue." (PMID 20544021, 2010).
prostate tumor (5 papers, 2013 to 2022). "Numerous studies investigating GSTP1, RARB and RASSF1 DNA promoter methylation have reported that hypermethylation in prostate tumour tissue may represent a biomarker of early cancer diagnosis, in accordance with our results." (PMID 27576364, 2016).
thyroid (5 papers, 2011 to 2024). "Our data suggests that aberrant methylation of CASP8, RASSF1, and NIS maybe an early change in thyroid tumorigenesis regardless of cell type." (PMID 21738852, 2011).
kidney cancer (4 papers, 2010 to 2025). Primary or metastatic malignant neoplasm involving the kidney. "The RASSF1 gene, located at 3p21.3, is silenced in a variety of human cancers, including lung, bladder, prostate and kidney cancers." (PMID 24959214, 2014).
pancreatic endocrine tumor (4 papers, 2011 to 2019). "Ras-associated domain family 1 (RASSF1) is frequently hypermethylated in pancreatic NETs—75% of 48 well-differentiated tumors demonstrated hypermethylation at this site, with no hypermethylation in adjacent normal tissue." (PMID 29255447, 2017).
renal carcinoma (4 papers, 2016 to 2018). A carcinoma arising from the epithelium of the renal parenchyma or the renal pelvis. "Hypermethylation on cfDNA was detected for the LRRC3B (74.1%), APC (51.9%), FHIT (55.6%), and RASSF1 (62.9%) genes in patients with renal cancer." (PMID 27725787, 2016). "The results obtained indicate that the concentration of cell-free DNA in plasma and the methylation of specific genes (such as FHIT, APC, and RASSF1) can be a significant addition to serological tumor markers in the identification of patients with renal cancer." (PMID 27725787, 2016).
asthma (3 papers, 2015 to 2025). "Interestingly, the pathway “role of APC in cell cycle regulation” has not been listed as significant asthma-related pathway in the GeneGo collection yet, as only one object of this pathway (RASSF1) has been described to be associated with asthma." (PMID 26292153, 2015).
colorectal adenocarcinoma (3 papers, 2016 to 2025). The most common type of colorectal carcinoma. "An analysis of RASSF1 expression profiles in colorectal adenocarcinoma (COAD) and rectal adenocarcinoma (READ) by the GEPIA web-based tool revealed modest underexpression in patients, though this was not statistically significant." (PMID 40004552, 2025).
cutaneous melanoma (3 papers, 2015 to 2021). A primary melanoma arising from atypical melanocytes in the skin. "Our group has previously demonstrated the correlation between transcriptional inactivation of the RASSF1 gene in cutaneous melanoma and hypermethylation of CpG promoter region, and relation to disease progression." (PMID 26334503, 2015). "Our group previously demonstrated that the RASSF1 gene has a significant tumor suppressor role in cutaneous melanoma." (PMID 26334503, 2015).
differentiated thyroid carcinoma (3 papers, 2004 to 2025). Differentiated thyroid carcinoma (DTC), also known as papillary or follicular thyroid carcinoma, is a slow-growing malignancy usually presenting in adults as an asymptomatic thyroid mass. "For example, in one study, high RASSF1 methylation of the CpG island in the RASSF1A promoter was found in all patients with PDTC and in 78% of ATC cases, but it was relatively low in differentiated thyroid cancer." (PMID 40819127, 2025).
follicular thyroid cancer (3 papers, 2014 to 2024). "Together, in this study, RASSF1, DAPK1 and ESR1 suggest utility of methylation markers to molecularly differentiate follicular thyroid cancer subtypes for enhanced classification." (PMID 27158284, 2015).
leiomyosarcoma (3 papers, 2013 to 2018). An uncommon, aggressive malignant smooth muscle neoplasm, usually occurring in post-menopausal women. "Activated MTOR/AKT1 signaling, RASSF1 hypermethylation and MYC expression can also be found in a subset of leiomyosarcomas." (PMID 29881541, 2018).
leukaemia (3 papers, 2009 to 2015). "We investigated the CpG island methylation status of the 'classical' RASSF members, RASSF1–6, in a large series of childhood ALL to ascertain whether epigenetic inactivation of these genes occurs in childhood leukaemia." (PMID 19570220, 2009). "Surprisingly, we found that RASSF1–5 were infrequently methylated whilst RASSF6 was methylated in B-ALL (94%; 48/51), T-ALL (41%; 12/29) and 5/5 unclassified childhood leukaemias but not in normal blood or bone marrow control samples (0/8 and 0/1 respectively)." (PMID 19570220, 2009).
thyroid tumor (3 papers, 2015 to 2024). A benign or malignant neoplasm affecting the thyroid gland. "There have been several reports on RASSF1 promoter hypermethylation in thyroid tumors including comparisons between FTCs and their corresponding normal tissues utilizing non-quantitative methods such as MSP." (PMID 27158284, 2015). "They found concordance between methylation of RASSF1 and decreased protein expression in the thyroid tumors." (PMID 27158284, 2015).
anaplastic thyroid cancers (2 papers, 2015 to 2019). "CpG island methylation of tumor-related promoters including RASSF1, MGMT, and SLC5A8 occurs preferentially in undifferentiated thyroid carcinoma." (PMID 31754358, 2019).
cholangiocarcinoma (2 papers, 2013 to 2018). A carcinoma that arises from the intrahepatic biliary tree (intrahepatic cholangiocarcinoma) or from the junction, or adjacent to the junction, of the right and left hepatic ducts (hilar cholangiocarcinoma). "In cholangiocarcinoma, miR-148a and miR-152 target DNMT1; reduced expression of these miRNAs contributes to increased DNMT1 activity, which affects transcription of the tumor suppressor genes Ras association domain family member 1 (RASSF1A) and cyclin-dependent kinase inhibitor 2A (p16INK4a)." (PMID 29401683, 2018).
chronic myelogenous leukaemia (2 papers, 2022 to 2024). "Moreover, bosutinib, a tyrosine kinase inhibitor, is perhaps the best candidate identified, as it is already in use against chronic myeloid leukemia and was found to target five upregulated proteins (CDC37, CDKN1B, GRB2, RASSF1, and SMAD2)." (PMID 39202022, 2024). "Therefore in this study, we determined the DNA methylation status at CpG dinucleotides of DAPK1, RASSF1, p16INK4, p14ARF, RIZ1 and SOCS1 in concert with disease progression, imatinib response and overall survival in chronic myelogenous leukaemia." (PMID 35421941, 2022).
ependymoma (2 papers, 2009 to 2022). A WHO grade II, slow growing tumor of children and young adults, usually located intraventricularly. "The tumors suppressor genes RASSF1, CDKN2A, CDKN2B, p14ARF and TP73, as well as other genes potentially involved in the tumorigenesis of ependymomas, such as CASP1, MGMT, TIMP3 and THBS1 are epigenetically silenced by aberrant promoter methylation in subsets of ependymomas." (PMID 19333441, 2009).
germinoma (2 papers, 2011 to 2020). A malignant germ cell tumor arising in the central nervous system. "While this particular sample showed higher expression of GATA6, FOXA2, or HNF4A and hypermethylation of RASSF1, RUNX3, HIC1, or APC, its methylation pattern was partially common to that of germinomas or ECs." (PMID 32999426, 2020).
mouth neoplasm (2 papers, 2014 to 2022). "Nonetheless, the methylation of other genes in mouth neoplasm such as APC, DAPK, ECAD, RASSF1, TIMP3 and p16, have retrieved more promising diagnostic and prognostic values." (PMID 35888599, 2022).
neuroendocrine tumors (2 papers, 2018 to 2020). "RASSF1 methylation increased with tumor type and grade (p<0.001) with strongest methylation in neuroendocrine tumors (NET)." (PMID 29851970, 2018).
schizophrenia (2 papers, 2022 to 2025). A major psychotic disorder characterized by abnormalities in the perception or expression of reality. "It is assumed that variation in the RASSF1 gene increases apoptosis of excess nerve cells, resulting in decreased nerve cell function and association with schizophrenia." (PMID 35528814, 2022). "We noted a notable association of multiple SNPs in RASSF1 and MRTFA with psychological traits schizophrenia, neuroticism, and depression." (PMID 39951537, 2025). "Therefore, further investigations on COMT, RASSF1 and GPM6A on larger population are warranted to validate our findings and further elucidate the association between schizophrenia and variations in these genes." (PMID 35528814, 2022).
acute lymphoblastic leukemia (1 paper, 2010). Leukemia with an acute onset, characterized by the presence of lymphoblasts in the bone marrow and the peripheral blood. "We have recently described an epigenetic profile of the RASSF1-10 genes in childhood acute lymphoblastic leukemia (ALL)." (PMID 20184741, 2010).
atrial fibrillation (1 paper, 2024). A disorder characterized by an electrocardiographic finding of a supraventricular arrhythmia characterized by the replacement of consistent P waves by rapid oscillations or fibrillatory waves that vary in size, shape and timing and are accompanied by an irregular ventricular response. "The higher the level of DNA methylation modification of some important genes (NPPA, NPRA, NPR-C, RASSF1 A) may be more likely to induce atrial fibrillation." (PMID 38765775, 2024).
chordoma (1 paper, 2013). Chordomas are rare malignant tumors arising from embryonic remnants of the notochord in axial skeleton. "By comparing methylation patterns of blood from healthy individuals and chordoma patients we found 20 significantly differentially methylated genes; 15 hypermethylated in chordoma (for example RASSF1, KL, RARB, HIC1, and FMR1) and 5 hypomethylated (HSD17B4, BAZIA, STAT1, NEUROGL, and JUP)." (PMID 23533570, 2013).
chronic hepatitis C (1 paper, 2013). "In chronic hepatitis C patients, methylation frequencies in many TSGs, such as RASSF1, CDKN2A, APC, and RUNX3, were associated with shorter time-to-HCC occurrence." (PMID 24330717, 2013).
colorectal adenoma (1 paper, 2007). An adenoma that arises from the colon or rectum. "In this study, therefore, we investigated K-ras and BRAF mutations and the methylation status of RASSF1 and RASSF2 in colorectal adenoma samples." (PMID 17923875, 2007). "We analysed K-ras/BRAF mutations and the methylation status of RASSF1 and RASSF2 promoter regions in 120 colorectal adenomas with respect to their clinicopathological features." (PMID 17923875, 2007). "In the current study, we examined K-ras/BRAF mutations and methylation status of RASSF1 and RASSF2 in colorectal adenomas in relation to clinicopathological features." (PMID 17923875, 2007).
endocrine cancers (1 paper, 2013). "Hypermethylation of the RASSF1 promoter responsible for RASSF1A expression has a well-established role in tumor progression in several organ systems and tissue types, including several endocrine tumors." (PMID 23915220, 2013).
gastric leiomyoma (1 paper, 2014). A rare benign smooth muscle neoplasm arising from the wall of the stomach. "Note that neither RASSF1, p16, nor p73 is methylated in the studied gastric leiomyoma." (PMID 25544907, 2014).
goiter (1 paper, 2019). Enlargement of the thyroid gland usually caused by lack of iodine in the diet, hyperthyroidism, or thyroid nodules. "Our data showed that the promoter methylation of SLC5A8, Ras association domain family member 1(RASSF1), and MGMT were significantly different between PTC tissue and goiter with P-value less than 0.05." (PMID 31754358, 2019). "The most significant differences were observed in RASSF1; 77.2% of hyper-methylated PTC patients versus 15.6% hyper-methylated goiter samples (P<0.001)." (PMID 31754358, 2019). "In this research, we determined the promoter methylation status of four tumor suppressor genes (SLC5A8, RASSF1, MGMT, and DNMT1) and compared the results of 55 PTC cases with 40 goiter patients." (PMID 31754358, 2019). "However, our results indicated that DNMT1 methylation in PTC patients, in comparison with goiter patients (controls), was less than SLC5A8, RASSF1, and MGMT." (PMID 31754358, 2019).
lung carcinoids (1 paper, 2019). "RASSF1 promoter hypermethylation was found as the most frequent epigenetic event reported in both typical and in atypical lung carcinoids and it was associated with tumor grade but without a linear correlation between levels of methylation and RASSF1A mRNA or protein content." (PMID 31126053, 2019).
Myocardial fibrosis (1 paper, 2022). "RASSF1-AS1 binds to RASSF1 mRNA to promote NF-κB activation and inhibit the translation of RASSF1A, thus exacerbating myocardial fibrosis in mice, indicating a potential application of RASSF1-AS1 as a therapy target for myocardial fibrosis." (PMID 35578250, 2022).
neuroendocrine tumors of the lung (1 paper, 2016). "For example, RASSF1 is a TSG mainly reported in neuroendocrine tumors of the lung." (PMID 26590405, 2016).
pancreatic ductal adenocarcinoma (1 paper, 2016). An infiltrating adenocarcinoma that arises from the epithelial cells of the pancreas. "The Ras Association Domain Family Member 1 (RASSF1) is one of the most frequently reported methylation-inactivated tumor suppressor genes in primary pancreatic ductal adenocarcinomas (PDAC)." (PMID 26754001, 2016).
pharyngeal tumors (1 paper, 2009). "The promoter methylation status of the DNA repair gene MGMT and the tumor suppressor genes CDKN2A and RASSF1 were evaluated by methylation-specific PCR in 88 primary oral and pharyngeal tumors and correlated with survival and tumor recurrence." (PMID 19807915, 2009). "We evaluated 88 primary oral and pharyngeal tumors for methylation of the promoter for the DNA repair gene MGMT and the tumor suppressor genes CDKN2A and RASSF1 using methylation-specific PCR." (PMID 19807915, 2009).
renal papillary cell carcinoma (1 paper, 2020).
synovial sarcoma (1 paper, 2024). "According to Array comparative genomic hybridization (CGH) results, it has been reported that there is a loss of RAS association domain family 1A (RASSF1) in patients with synovial sarcoma and that RASSF1 loss is associated with low RASSF1A protein level." (PMID 38681356, 2024).
ZIKV infection (1 paper, 2019). "DNA methylation profiling reveals that ZIKV infection induces hypermethylation on genes of key signaling molecules in the Hippo signaling pathway, such as TAZ and RASSF1, resulting in a decrease in the protein expression." (PMID 32038526, 2019). "ZIKV infection induces hypermethylation of TAZ and RASSF1; YAP/TAZ and phosphorylated YAP/TAZ levels are significantly reduced in hNPCs after ZIKV infection." (PMID 32038526, 2019).